CCDC68 (coiled-coil domain containing 68)
Description:
Centriolar protein required for centriole subdistal appendage assembly and microtubule anchoring in interphase cells. Together with CCDC120, cooperate with subdistal appendage components ODF2, NIN and CEP170 for hierarchical subdistal appendage assembly.
Synonyms: SE57-1
Tractability: No criterion of Open Targets' tractability assessment is met for any kind of drug.
Gene: Protein-coding gene on chromosome 18 (54,901,504 to 54,959,519, reverse strand). Ensembl gene ENSG00000166510.
Subcellular location: Cytoplasm, cytoskeleton, microtubule organizing center, centrosome, centriole
Subcellular location (Human Protein Atlas): Golgi apparatus; Cytosol
Gene Ontology:
Molecular function: protein binding
Biological process: intracellular protein localization; microtubule anchoring at centrosome
Cellular component: centriolar subdistal appendage; centriole
Genetic constraint (gnomAD): Loss-of-function variants: 8 observed, 15.63 expected, observed/expected ratio (o/e) 0.51, 90% interval 0.3 to 0.92. The upper end of that interval is the gene's LOEUF score, 0.92, which puts it in group 3 of 6, group 1 being the genes least tolerant of losing a copy. Missense variants: 126 observed, 147.17 expected, observed/expected ratio (o/e) 0.86, 90% interval 0.74 to 0.99. Synonymous variants: 55 observed, 51.74 expected, observed/expected ratio (o/e) 1.06, 90% interval 0.86 to 1.33.
Homologues: Orthologues: chimpanzee CCDC68 (99% identical), macaque CCDC68 (97% identical), pig CCDC68 (84% identical), dog CCDC68 (83% identical), guinea pig CCDC68 (82% identical), rabbit CCDC68 (82% identical), mouse Ccdc68 (72% identical), rat Ccdc68 (71% identical), tropical clawed frog ccdc68 (45% identical). Paralogues in human: MYZAP (26% identical), TUFT1 (21% identical), POLR2M (8% identical).
Diseases named in the same sentence as CCDC68 in open-access papers:
CCDC68 is named in the same sentence as 16 diseases in open-access papers, as found by Europe PMC text mining. Sharing a sentence is not in itself a finding about the gene and the disease. The quoted sentences say what the papers report.
colorectal cancer (3 papers, 2021 to 2024). A primary or metastatic malignant neoplasm that affects the colon or rectum. "To further assess the involvement of CCDC68 in tumor growth regulation, we injected wild‐type and CCDC68‐knockout HCT116 cells into nude mice to establish colorectal cancer xenograft mouse models." (PMID 39018254, 2024). "Coiled-coil domain-containing 68 (CCDC68) plays different roles in cancer and is predicted as a tumor suppressor in human colorectal cancer (CRC)." (PMID 33968776, 2021).
lung carcinoma (3 papers, 2021 to 2024). "Our analysis revealed that lower mRNA expression of CCDC68 was significantly associated with higher aneuploidy in colorecal, breast, and lung carcinomas." (PMID 39018254, 2024). "CCDC68 is upregulated in NSCLC, and downregulating CCDC68 expression decreases cell proliferation and increases apoptosis, suggesting that CCDC68 is a candidate biomarker for the detection of malignant transformation in lung cancer." (PMID 33968776, 2021). "CCDC68 was positively correlated with MSI-pRS and is a tumor-suppressive gene by reducing cell proliferation and enhancing apoptosis, which is strongly expressed in the lung cancer tissues." (PMID 36873930, 2023).
pancreatic ductal adenocarcinoma (3 papers, 2016 to 2025). An infiltrating adenocarcinoma that arises from the epithelial cells of the pancreas. "Overexpression of the coiled coil domain protein CCDC68 decreased proliferation and tumorigenicity of pancreatic ductal adenocarcinoma cells while allelic loss was found in about half the tumors examined." (PMID 27144453, 2016). "While CCDC68 acts as a pro-carcinogenic factor in IL-6-stimulated endometrial cancer cells, it also exhibits tumor-suppressor properties in pancreatic ductal adenocarcinoma." (PMID 40547309, 2025). "An unstable isoform of CCDC68 (CCDC68Δ69–114) that lacks tumour-suppressive ability has been reported in 31% of pancreatic ductal adenocarcinoma patients." (PMID 28422092, 2017).
insomnia (1 paper, 2020). A sleep disorder characterized by difficulty in falling asleep and/or remaining asleep. "Notably, two loci COMT (catechol-O-methyltransferase) and CCDC68 (coiled-coil domain containing 68) have previously been associated with sleep disturbance and insomnia." (PMID 33192958, 2020).
lung squamous cell carcinoma (1 paper, 2025). "Pan-cancer analysis showed that CCDC68, FAM151A and MC1R were significantly different in thyroid cancer (THCA), renal clear cell carcinoma (RCC) and lung squamous cell carcinoma (LUSC) etc.." (PMID 40547309, 2025).
pancreatic cancer (1 paper, 2021). "However, CCDC68 plays a tumor-inhibitory role in pancreatic cancer, which is inconsistent with the tumor-promoting function of CCDC68 in NSCLC." (PMID 33968776, 2021).
schizophrenia (1 paper, 2013). A major psychotic disorder characterized by abnormalities in the perception or expression of reality. "Unfortunately, in our sample sizes, there was no allelic association with schizophrenia for any of the five SNPs [rs7914558 (CNNM2), rs10503253 (CSMD1), rs7004633 (MMP16), rs11191580 (NT5C2) and rs12966547 (CCDC68)] (p > 0.22)." (PMID 24160291, 2013).
cancer (7 papers, 2019 to 2025). A tumor composed of atypical neoplastic, often pleomorphic cells that invade other tissues. "Likewise, mutations in CCDC68 involving microtubule organization have been reported in different cancer types." (PMID 35216305, 2022). "CCDC68 is a putative tumor suppressor gene in several types of cancer, partly through regulating the cell cycle by controlling the degradation of CDK4." (PMID 35976950, 2022). "In sum, CXCL3, SLC7A5, SLC26A2, GART, and CCDC68 genes were differentially expressed in three or more cancer types." (PMID 29843204, 2019). "This suggests that CCDC68 plays different roles in various human cancers." (PMID 33968776, 2021). "Therefore, the role of CCDC68 in cancer remains controversial." (PMID 33968776, 2021). "CCDC68‐knockout HCT116 cells showed a reduced clonogenic ratio and attenuated resistance to taxol, further suggesting that CCDC68 contributes to cell survival and SAC activation in cancer cells with low aneuploidy rates." (PMID 39018254, 2024). "We observed that the protein levels of CDC20 and BUBR1 were decreased by ≈50% in CCDC68‐knockout HCT116 cells during late prometaphase, suggesting that CDC20 and BUBR1 protein levels were at least partly maintained by CCDC68 in cancer cells with low aneuploidy rates." (PMID 39018254, 2024).
tumor (7 papers, 2017 to 2025). "The results showed that CCDC68 was significantly downregulated in tumor tissues, which was consistent with TCGA data." (PMID 33968776, 2021). "The results showed that CCDC68 expression was lower in human CRC than in paired non-tumor tissues, and analyses of a human CRC database and cell lines supported the low expression of CCDC68 in CRC." (PMID 33968776, 2021). "The data suggested that CCDC68 acts as a tumor suppressor in CRC and has a potential prognostic role in predicting survival." (PMID 33968776, 2021). "CCDC68 was downregulated in CRC, and functional experiments showed that CCDC68 inhibited CRC cell growth in vitro and tumor formation in vivo." (PMID 33968776, 2021). "The present results indicate that CCDC68 is an important tumor suppressor molecule in CRC, and CCDC68 and its downstream effectors may become potential targets for the early diagnosis and/or treatment of CRC." (PMID 33968776, 2021). "CCDC68 may contribute to CRC pathogenesis via multiple signaling pathways, and functional experiments demonstrate its inhibitory effects on CRC cell growth in vitro and tumor formation in vivo." (PMID 40547309, 2025). "We found two deleted regions shared by both tumor types in three out of the four cell lines H23R, A2780R, and OVCAR3R, but not in H460 cells, located on 18q21.2–18q21.31 and 18q21.32, affecting the genes RAB27B, CCDC68, TCF4, TXNL1, WDR7, and BOD1P; and genes ZNF532, SEC11C, GRP, respectively." (PMID 32224864, 2020). "In comparison with full-length CCDC68, CCDC68Δ69–114 showed similar SDA localization and CEP170-binding ability, suggesting that the tumour-suppressive function of CCDC68 may not rely on its functions at SDAs." (PMID 28422092, 2017).
CCDC68 also shares sentences with these, for which no sentence is quoted: colon cancer (1 paper); endometrial cancer (1); gastric cancer (1); hearing loss (1); lung adenocarcinoma (1); renal clear cell carcinoma (1); thyroid cancer (1).